IL10 (interleukin 10)
Diseases named in the same sentence as IL10 in open-access papers (continued):
Sharing a sentence is not in itself a finding about the gene and the disease.
liver fibrosis (continued). "Common features of the top three pathways for KD (Trem1 signaling, Hepatic fibrosis, and IL-10 signaling) and the other groups were the abundance of transcripts related to the activation of the Nlrp3 inflammasome, including Il-1 and caspase-1 related transcripts." (PMID 25614765, 2014). "It is possible that IL-10+ Bregs and TFR cells may secrete TGF-β1, which activates the Smad signaling to promote liver fibrosis and to induce other unknown factors, causing liver injury in those CHB and CHC patients." (PMID 25199644, 2014). "However, little is known regarding the effect of rat interleukin-10 (rIL-10) gene by hydrodynamics-based transfection (HBT) on liver fibrosis in rats." (PMID 24993843, 2014). "Increasing IL-10 levels could inhibit the formation of liver fibrosis and protect liver function." (PMID 38769368, 2024). "Similarly, bone marrow MSCs transplantation can alleviate liver fibrosis by promoting the phenotypic shift of monocytes from the pre-fibrotic Ly6Chi subpopulation to the restorative Ly6Clow subpopulation through paracrine secretion of IL-4 and IL-10." (PMID 35895169, 2022). "Furthermore, exogenous IL-10 can ameliorate CCl4-induced hepatic fibrosis in rats." (PMID 36362037, 2022). "Thus, the BAT–liver axis may serve as a potential therapeutic target for liver fibrosis, and IL-10 may be a key factor regulating the activation of HSCs by BAT." (PMID 34124102, 2021). "Therefore, increasing numbers of studies have aimed to use IL-10 gene transfer and IL-10 gene therapy might be an effective treatment for liver fibrosis." (PMID 33841164, 2021). "Genistein protected against liver fibrosis caused by S. japonicum and decreased the extent of hepatic granuloma via inhibiting activation of NF-κB signaling pathway and led to downregulation of inflammatory cytokines MCP1, TNFα, IL1β, IL4, IL10 in infected mice." (PMID 32410640, 2020). "In other studies with animal models, the absence of IL-10 was associated with liver fibrosis." (PMID 33125400, 2020). "However, specific immune response pathways like MHC based antigen presentation, interferon signaling and hepatic fibrosis were associated with radiation responsive genes in Il10−/− mice but not WT mice." (PMID 31046668, 2019). "A decrease in the number of Tregs further leads to reduced secretion of IL-10 and a weaker anti-fibrotic effect, while an increase in the number of Th17 cells further leads to increased IL-17 secretion and a profibrotic effect, resulting in aggravated liver fibrosis, promoting a vicious cycle." (PMID 31639000, 2019). "The protective function of MSCs in liver fibrosis as well as liver inflammation could be explained by the modulatory effect of MSCs via paracrine mechanisms on reducing the function of activated hepatic stellate cells (HSCs) through secretion of IL-10." (PMID 30346985, 2018). "Also, inhibition on liver fibrosis could be IL-10 dependent, as shown that the expression of α-SMA by LX-2 cells was decreased when treated with IL-10." (PMID 29312539, 2017). "JIB-04, an H3K36me3 agonist, effectively suppressed KC activation induced by Men1 or Setd2 deletion by reactivating IL-10 expression and further alleviated CCL4-induced liver fibrosis symptoms." (PMID 40651612, 2025). "Aapelin/APLNR promotes the migration and activation of B cells, which results in the expression of cytokines such as AHNAK, COL6A3, IL10, IRF9 and RFX2, affecting liver fibrosis in MASLD." (PMID 40761743, 2025). "The expression of CCR2 and IL-10 in Tregs enhanced by HSCs can equivalently inhibit IFN-γ production in NK cells to promote aHSCs apoptosis and inhibit HSCs activation, attenuating liver fibrosis." (PMID 40761743, 2025). "A study reported that using IL-10-modified bone marrow-derived DCs, where the DCs were immature and infused into CCL4-induced hepatic fibrotic mice, significantly alleviated liver fibrosis." (PMID 39995661, 2025).
liver fibrosis (continued). "It has also been demonstrated that cytokines such as IL-13, transforming growth factor (TGF)-β1 and tumor necrosis factor (TNF)-α promote hepatic fibrosis, while cytokines such as interferon (IFN)-γ and IL-10 inhibit hepatic fibrosis." (PMID 38086792, 2023). "Oxymatrine reduces liver fibrosis by limiting the pro-inflammatory cytokines, interleukin-6 and TNF-α generated by carbon tetrachloride and boosting anti-inflammatory factors such as interleukin-10." (PMID 36985782, 2023). "Prior studies have shown that IL10 inhibits cytokine production, regulates T cell immunity, thus facilitates immune tolerance, and persists HBV infection advancing hepatic fibrosis." (PMID 35308519, 2022). "MSCs or MSC-conditioned medium (MSC-CM) treatment increased IL-10 and IDO levels in serum and ameliorated CCl4-induced liver fibrosis through downregulating IL-17 producing CD4+ T cells and upregulating IL-10 producing CD4+ T cells in the liver." (PMID 36248254, 2022). "Although the relationship between PPBP levels and platelet counts or IL-10 levels requires further investigation, we have revealed for the first time that serum PPBP levels decrease with the progression of liver fibrosis." (PMID 35797333, 2022). "Interleukin‐10 (IL10) is a cytokine produced by numerous activated immune cells such as B cells, mast cells, granulocytes, macrophages, DCs, and multiple T cell subsets, with plural and diverse cellular functions, and may play a beneficial preventive role in hepatic fibrosis." (PMID 36176604, 2022). "CD4+ memory static T cells secrete iconic cytokines IL-4, IL-10, and IFN-G, and stimulate other immune cells such as NK cells, to media the progress of liver fibrosis." (PMID 36686655, 2022). "By secreting IL-10 and TGF-β, M2 macrophages are involved in the formation of scar granuloma and liver fibrosis by mediating smooth muscle cells and endothelial cells." (PMID 35324411, 2022). "In this context, the authors indicated that IL-17 levels (as a part of other secreted ILs as IL-6, IL-10, IL-21, IL-1β and INF-γ) increased in CHC and its level correlated directly with the degree of liver fibrosis." (PMID 35056005, 2022). "MSCs drastically alleviated CCl4-mediated liver fibrosis by lowering the proportion of Th17 cells and elevating the levels of CD4+IL-10+ T cells as well as the levels of immune suppressive factors, including kynurenine, IDO, and IL-10." (PMID 35841079, 2022). "Higher levels of IL-9, IL-10, and IL-17 were found in PBMC supernatants of patients with advanced hepatic fibrosis." (PMID 34970264, 2021). "A series of studies from Ling's team suggested that 800 mg/kg dietary cyanidin-3-O-β-glucoside alleviated liver fibrosis by suppressing inflammatory factors, such as TNF-α, IL-6, and IL-10." (PMID 33082829, 2020). "Chronic stimulation of anti‐inflammatory (IL‐4, IL‐10, IL‐13 and TGF‐β1) factors is related to liver fibrosis progression." (PMID 31755616, 2020). "Many small molecules are important triggers of liver fibrosis, such as tumor necrosis factor-alpha (TNF-α), interleukin-10 (IL-10), and transforming growth factor-beta (TGF-β), which possess effective pro-inflammatory or anti-inflammatory effects." (PMID 32226380, 2020). "In the present study, we identified a mixed profile of elevated circulating inflammatory cytokines, chemokines, and growth factors, including IL-6, IL-10, IFN-γ, GM-CSF, and FGF-basic, among HIV–HCV-coinfected patients with advanced liver fibrosis." (PMID 33348839, 2020). "In a CCl4-induced liver fibrosis model, hesperidin at 200 mg/kg decreased lipid peroxidation, NF-κB, TGF-β, CTGF, and IL-1β and increased IL-10 expression." (PMID 33082829, 2020). "In contrast to IL-10, the signaling of LPS/TLR4 in hepatic stellate cells plays a crucial role in the progression of liver fibrosis by inducing the expression of cytokines/chemokines that recruit KC cells, which secrete the profibrogenic cytokine TGF-β." (PMID 30022981, 2018).
liver fibrosis (continued). "Taken together, these findings indicate that IL-10/STAT3 activation mediates IL-17A-suppressed autophagy and participates in the development of hepatic fibrosis." (PMID 28039485, 2017). "Alternately, treatment with IL-10 has been demonstrated to significantly increase the production of MMPs, including MMP-9, as well as significantly decrease TIMPs during liver fibrosis." (PMID 27681697, 2016). "Patients with severe liver fibrosis presented lower frequency of circulating CD8+ T-cells, higher levels of proinflammatory cytokines, but lower levels of IL-10, in addition to the higher viral load." (PMID 26742960, 2016). "Animal studies have demonstrated that chronic vitamin D deficiency or the deletion of Vdr−/− gene in mice lead to spontaneous development of liver fibrosis with abnormal increase in the levels of TGF-β1 and IL-6 as well as a significant decrease in IL-10." (PMID 27681697, 2016). "On the contrary, IL-10 gene therapy reduced the expression of profibrotic genes, including TGF-β and TNF-α, and reversed the thioacetamide-induced hepatic fibrosis in mice." (PMID 26199463, 2015). "Retinoic acids in HSCs also stimulate interleukin-10 (IL-10) production by infused Gr1+CD11b+ bone marrow cells, subsequently suppressing HSC activation and liver fibrosis." (PMID 26024318, 2015). "As a key negative feedback regulator, IL-10 prevents the onset and progression of liver fibrosis by inhibition the release of inflammatory mediator, suppressing NF-κB activity, and acting through other mechanisms to protect the liver." (PMID 39995661, 2025). "In a mouse model of liver fibrosis induced by BDL, IL-10 was highly expressed in HSCs." (PMID 39995661, 2025). "Indeed, JIB-04, an H3K36me3 agonist, effectively suppressed KC activation by reactivating IL-10 expression and alleviated symptoms of CCL4-induced liver fibrosis." (PMID 40651612, 2025). "As a result, several other cytokines, such as TGF-β, IL-22, IL-10, and IL-6, which are known to play important roles in liver fibrosis, were not covered, as they were not addressed in the eligible studies." (PMID 40362271, 2025). "Additionally, PIC displayed anti-inflammatory and hepatoprotective effects in liver fibrosis induced by thioacetamide by repressing TGF-β1 and α-SMA expression, developing MDA, and improving interleukin-10 secretion." (PMID 37893021, 2023). "The improvement of liver fibrosis after treatment was associated with the presence of allele A of TNF-α-308 G/A and non-improvement with haplotype TT/GG of IL-10-592 G/T and IL-10-1082 T/C." (PMID 36674897, 2023). "Lack of improvement of liver fibrosis was associated with lower baseline values of platelet count for genotypes TNF-α-308 G/A_GG and haplotype TT/GG of IL-10-1082 T/C and IL-10-592 G/T." (PMID 36674897, 2023). "The global cytokine surveys of HSC-CM have demonstrated that TNF-α, agrin, PDGF, activin A, GM-CSF, IFN-γ, IL-1β, IL-4, IL-6, IL-10, IL-13, and TIMP-1, which subsequently induce acute inflammation and liver fibrosis, were elevated in aHSC-CM relative to the qHSC-CM." (PMID 36142683, 2022). "MSCs could also promote mobilization of Kupffer cells in vitro and in vivo and induce M1 to M2 conversion by increasing IL-4 and IL-10 secretion, thereby alleviating dimethylnitrosamine (DMN)-induced liver fibrosis." (PMID 35895169, 2022). "MSCs significantly alleviated CCl4-mediated liver fibrosis by decreasing the proportion of Th17 cells and increasing the levels of CD4+IL-10+ T cells and immunosuppressive factors (including kynurenine, IDO, and IL-10)." (PMID 36685534, 2022). "Tim-3 may promote the progression of liver fibrosis by regulating the secretion of cytokines (TNF-α, IL-10, and IFN-γ) by immune cells, thereby regulating the progression of liver disease." (PMID 35646962, 2022).
liver fibrosis (continued). "We found that an effective antiviral therapy of chronic HCV infection decreases the frequencies of T-cells expressing exhaustion markers and lowers plasma concentrations of IL-10, but these effects are absent in patients with advanced liver fibrosis." (PMID 32994477, 2020). "Furthermore, we detected the levels of TLR4, NF-κB, TNF-α, TGF-β, IL-10, α-SMA, and collagen I to study the degree of liver fibrosis in rats." (PMID 32226380, 2020). "Further, liver fibrosis and non-alcoholic steatohepatitis (NASH) lead to the accumulation of liver resident IgA+PD-L1+IL-10+ cells that directly impair CTL/CD8+ T cell functions against tumor-associated antigens, resulting in the development of hepatocellular carcinoma (HCC)." (PMID 32676074, 2020). "Such increased production of IL10 and IL13 can be yet another pathway of limiting liver fibrosis." (PMID 32373617, 2020). "Peng's research demonstrated that 70 mg/kg baicalin had a significant effect on CCl4-induced liver fibrosis, which was correlated with immunoregulation of the imbalance between profibrotic and anti-fibrotic cytokines, including TGF-β1, TNF-α, IL-6, and IL-10 expression." (PMID 33082829, 2020). "These B1 cells secrete IL-10, which inhibits expression of key chemokine CCL2 to limit excessive liver infiltration of Ly6Chi monocytes and thereby alleviate early inflammation and later liver fibrosis." (PMID 31194740, 2019). "Meanwhile, slight expressions of TGF-β and IL-10 were identified in the liver without cysts nearby, demonstrating a tendency for the host affected by E. granulosus to develop liver fibrosis." (PMID 28464914, 2017). "In the progression of liver fibrosis, activated Kupffer and HSC cells secrete large amounts of IL-6 and TGF-β1, promote the transformation from Treg to Th17, resulting in reduced secretion of IL-10 and increased secretion of IL-17." (PMID 28646179, 2017). "To elucidate whether IL-10 and IL-6 are involved in the suppressing effect of EXE on hepatic fibrosis, we detected their serum levels in the control group and EXE-treated group." (PMID 29464186, 2017). "Treg cytokine IL-10, which has been coupled with the activation of JAK-STAT1 or STAT3 signaling cascade and found high expression in liver fibrotic tissues, was used to reverse therapeutic effect of IL-17A antibody in TAA-induced hepatic fibrosis mice." (PMID 28039485, 2017). "In addition, it was demonstrated a decrease in liver fibrosis in CHC patients treated with recombinant IL-1026, which supports the protective role of IL-10 for developing fibrosis." (PMID 29038590, 2017). "Liver fibrosis is influenced by tumor necrosis factor alpha (TNF-α) and interleukin 10 (IL-10)." (PMID 25013899, 2014). "Besides, gene expressions of Th1/Th2 cytokines such as IL-4, IL-10, IL-13 and IFN-γ, which were important in schistosomiasis liver fibrosis, were also detected in our experiment." (PMID 21629648, 2011). "Reducing inflammation and oxidative stress, SAG administration importantly reduced liver fibrosis, as confirmed by the decreased collagen deposition, assessed by Masson trichrome staining, and the reduced hydroxyproline contents and α-sma and TGF-β expressions, while it restored IL10 levels." (PMID 35457246, 2022). "In addition, PPBP expression is reportedly regulated by the anti-inflammatory cytokine IL-10, suggesting that the decrease in PPBP levels with the progression of liver fibrosis also reflects the increase in IL-10 production in response to the progression of fibrosis." (PMID 35797333, 2022). "Moreover, the dramatic increase in circulating IL-10 and its expression by the BAT in mice housed under TN conditions may be an adaptive response to attenuate liver fibrosis." (PMID 34124102, 2021).
liver fibrosis (continued). "The therapeutic effects of IL-10 were shown in experiments in vivo in which IL-10 gene therapy reduced the expression of fibrosis-related genes including TGF-β, TNF-α, and collagen α1, and also decreased the activation of α-SMA in thioacetamide-induced liver fibrosis." (PMID 33841164, 2021). "Thus, the lack of IL-10 induced brown adipocyte dysfunction, which exacerbated liver fibrosis in mice housed under thermoneutrality." (PMID 34124102, 2021). "Intrahepatic IL10 mRNA expression seems to reflect the blood pattern of this cytokine, corroborating a previous report in which HCV patients with severe fibrosis (F3-F4) had a lower frequency of intrahepatic T cells (especially Tregs) than patients with mild hepatic fibrosis." (PMID 33125400, 2020). "In summary, we found that a successful therapy of chronic HCV infection with DAA lowered expression of T-cell exhaustion markers to near normal values and reduced IL-10 levels in plasma, but these changes were largely confined to patients with minimal or no liver fibrosis." (PMID 32994477, 2020). "According to these results, we hypothesized that DC-IL10 but not DC-mock treatment could attenuate liver fibrosis by reducing proinflammatory factor levels which may relate to the high expression of IL-10." (PMID 30800002, 2019). "Similarly, human participants with severe hepatic fibrosis tend to express less IL-10 compared to nonfibrotic individuals." (PMID 29610679, 2018). "Therefore, IL-10 may serve as a critical factor linking BAT and liver fibrosis." (PMID 34124102, 2021).